IL32 (interleukin 32)
Diseases named in the same sentence as IL32 in open-access papers (continued):
Sharing a sentence is not in itself a finding about the gene and the disease.
chronic obstructive pulmonary disease (20 papers, 2011 to 2025). A chronic and progressive lung disorder characterized by the loss of elasticity of the bronchial tree and the air sacs, destruction of the air sacs wall, thickening of the bronchial wall, and mucous accumulation in the bronchial tree. "This study was to investigate the association between serum interleukin 32 (IL-32) concentration and clinical parameters in patients with stable chronic obstructive pulmonary disease (COPD)." (PMID 32694699, 2020). "Increased levels of IL-32 are present in the lungs of patients with chronic obstructive pulmonary disease and correlate with airflow decreases that are associated with this condition." (PMID 21649914, 2011). "Additionally, IL-32 has been implicated in other chronic diseases with increased CV risk, such as chronic obstructive pulmonary disease (COPD) and inflammatory bowel disease, reinforcing its broader role in systemic inflammation." (PMID 40299461, 2025). "Elevated IL-32 serum levels have been reported in chronic obstructive pulmonary disease, type 2 diabetes, HIV infection and MASLD." (PMID 37686029, 2023). "IL-32 mRNA isoforms have been studied so far in many different cell types and diseases including chronic obstructive pulmonary disease (COPD), various types of cancer and RA14,18–20." (PMID 30232372, 2018). "TNF-α and IL-32 are also critical mediators in some inflammatory diseases, including RA, chronic obstructive pulmonary disease, and graft-vs.-host disease." (PMID 29545920, 2018). "A recent study has proposed the role of IL-32 in chronic inflammatory diseases such as airway and lung diseases, including COPD (Chronic obstructive pulmonary disease)." (PMID 35983322, 2022). "IL-32 is also described as a proinflammatory cytokine, which appears to play a role in various inflammatory disorders such as chronic obstructive pulmonary disease (COPD) and atopic dermatitis." (PMID 29564208, 2018). "IL-32 is also mainly involved in major inflammatory diseases such as RA, IBD, and chronic obstructive pulmonary disease (COPD)." (PMID 26516703, 2015).
atherosclerosis (18 papers, 2014 to 2026). A disease characterized by the build-up of fatty material and calcium deposition in the arterial wall resulting in partial or complete occlusion of the arterial lumen. "Treatments that target interleukins, such as IL-27, IL-28, IL-29, IL-31, IL-32, and IL-33, have shown promise in reducing fibrosis and inflammation, two important processes linked to the development of heart disorders such as atherosclerosis and heart failure." (PMID 39844544, 2025). "We were prompted by recent evidence highlighting an association between endothelial and hepatocellular IL32 expression, correlating with circulating levels, with fatty liver disease, insulin resistance and atherosclerosis." (PMID 37108628, 2023). "IL-32 has previously been described to play a role in the pathogenesis of RA and additionally it has been suggested that IL-32 plays a role in atherosclerosis, presumably contributing to the increased CVD risk in this population." (PMID 28134327, 2017). "Furthermore, previous studies have already reported an association of IL32 with cardiovascular disease and atherosclerosis." (PMID 37108628, 2023). "We demonstrated that specific exogenous IL-32 isoforms (IL-32β and γ) have the potential to impact coronary artery endothelial cells leading to their dysfunction and recruitment of monocytes, two conditions linked with the development of atherosclerosis." (PMID 36992409, 2023). "Interleukin (IL)-32 has previously been shown to be involved in the pathogenesis of RA and might be linked to the development of atherosclerosis." (PMID 28134327, 2017). "Recent studies have shown that atherosclerosis maybe associated with IL-32 production." (PMID 25386048, 2014). "IL-32, a recently discovered cytokine, has emerged as a key player in the pathogenesis of cardiovascular diseases, including atherosclerosis, myocardial infarction, and heart failure." (PMID 42099604, 2026). "Our recent data demonstrated that the multi-isoform proinflammatory cytokine IL-32 is upregulated in PWH and is associated with arterial stiffness and subclinical atherosclerosis." (PMID 40214435, 2025). "Emerging biomarkers like IL-32, Dickkopf-related protein 1 (DKK-1), and galectin-3 also show potential in further refining risk assessment, particularly for atherosclerosis and myocardial fibrosis in rheumatic diseases." (PMID 40937212, 2025). "At the same time, IL-32 is also highly expressed in T cells and is known to play an important role in the late stage of atherosclerosis, characterized by plaque instability and rupture." (PMID 39095691, 2024). "The upregulation of these adhesion receptors by IL-32 isoforms suggests a potential role for IL-32 in recruitment of immune cells and the contribution to the pathogenesis of atherosclerosis." (PMID 36992409, 2023). "The induction of these chemokines further highlights the potential role of IL-32 in the pathogenesis of atherosclerosis given the high expression of this cytokine in the atherosclerotic lesions." (PMID 36992409, 2023). "IL-32 has been shown to promote angiogenesis on endothelial cells and leads to a modification of lipid profiles, linking it directly to atherosclerosis." (PMID 36769623, 2023). "An unbalanced regulation of the expression of IL32 isoforms by the endothelium has been involved in the pathogenesis of atherosclerosis, and in promoting endothelial inflammation and pre-eclampsia in pregnant women." (PMID 37108628, 2023). "Instead, the combined effect of intermittent hypoxia and IL-1β treatment led to the most pronounced expression of IL-19, IL-24 and IL-32 which are known to be dysregulated in inflammatory disorders, such as atherosclerosis." (PMID 37753073, 2023). "IL‐32 is also highly expressed in T cells, which play an important role in the late stages of atherosclerosis characterized by plaque instability and rupture." (PMID 34799941, 2022).
atherosclerosis (continued). "The role of IL-32 during the development of atherosclerosis has been illustrated, showing that IL-32 promotes angiogenesis on endothelial cells, suggesting IL-32 boosts the development of atherosclerosis." (PMID 34422917, 2021). "Taken together, the role of IL-32 during the development of atherosclerosis remains to be elucidated." (PMID 34422917, 2021). "The deleterious effects of chronic upregulation of IL-32 and IL-32-mediated chemokine expression may also expand beyond atherosclerosis." (PMID 36992409, 2023). "The known atherosclerosis gene IL32 was upregulated in DM- subjects compared to DM+ participants." (PMID 36077273, 2022). "Previous studies have shown that IL‐32 may be involved in the inflammatory cascade that leads to atherosclerosis and contributes to plaque instability by promoting the synthesis of matrix metalloproteinases." (PMID 34799941, 2022). "As the vascular endothelium is an important mediator in inflammation, IL‐32 as a critical regulator of endothelial cell (EC) functions may promote angiogenesis in endothelial cells, suggesting that IL‐32 boosts the development of atherosclerosis." (PMID 34799941, 2022). "Finally IL-32 and IL-37 may be protective while IL-34 may contribute to the development of atherosclerosis." (PMID 34422917, 2021). "However, we have reviewed the mechanisms of action of IL-32, -34 and -37 in atherosclerosis, allowing us to speculate on the possible pathogenesis of SARS-CoV-2 involvement in CVD." (PMID 34422917, 2021). "Through the method of bioinformatics, we finally obtained 10 hub genes in atherosclerosis and metabolic syndrome, and selected 3 of the most significant genes (CX3CR1, IL32, TLR5) for blood PCR verification." (PMID 39095691, 2024). "In this study, we aimed to investigate the potential impact of IL-32 isoforms on coronary artery endothelial cells (CAEC), whose dysfunction represents a major factor for atherosclerosis." (PMID 36992409, 2023). "In addition to Dpp4, there was an upregulation of a number of inflammation‐related genes including Card8, Card16, Gzma, Prf1, Il2rg, Il32, Cd52, and Ccl4 in CD4+ T cells isolated from patients with atherosclerosis." (PMID 36683148, 2023). "However, whether IL-32 contributes to the pathogenesis of atherosclerosis is not clear." (PMID 36992409, 2023).
lung carcinoma (18 papers, 2013 to 2025). "The T allele of the rs28372698 IL-32 polymorphism is associated with poor prognosis in patients with moderately and well-differentiated lung cancer." (PMID 38983267, 2024). "Expression of IL-32 is also associated with increased lung cancer invasiveness, metastatic ability and poor prognosis." (PMID 26395996, 2016). "Given that M. tuberculosis infections are risk factors associated with development of lung cancer, IL-32 was suggested as a possible link between chronic lung infection and lung cancer development." (PMID 26395996, 2016). "High expression of interleukin 32 (IL32) was shown to cause a worse clinical outcome in lung cancer patients." (PMID 23590835, 2013). "IL-32 subsequently activates the β5-integrin-Src-Akt pathway to reduce the sensitivity to the third-generation tyrosine kinase inhibitors (TKIs) in EGFR mutated lung cancer patients." (PMID 40248695, 2025). "Our data revealed that the CC genotype of rs12934561 in IL-32 was associated with an increased risk of BC, which is consistent with findings of previous studies in which the CC genotype was shown to relate closely with an increased susceptibility in lung cancer and endometrial cancer." (PMID 33204366, 2020). "Differential expression of IL-32 has been reported in various lung cancer histotypes, including small-cell lung cancers." (PMID 33287695, 2020). "The aptamer antagonized the functional activity of IL-32 and inhibited IL-32-dependent expression of TNFα in human lung carcinoma cells." (PMID 33266394, 2020). "Accordingly, an analysis of IL-32 immunoreactivity in lung cancer has shown that adenocarcinomas had strong overexpression of interleukin-positive cells while the most of squamous cell carcinoma samples were lacking IL32-immunoreactivity." (PMID 33020452, 2020). "In this study, we found that miR-19a or miR-19b-1 overexpression remarkably downregulated IL32 expression in lung cancer cells and led to an increase in IL32 expression in NPC cells." (PMID 32308549, 2020). "IL-32 ability to activate gene transcription factor—NF-κB, was propose to promote lung cancer progression." (PMID 26395996, 2016). "PCs exhibit a unique secretome, with high secretion of IL-32, in EGFR mutated lung cancer patients." (PMID 40248695, 2025). "Moreover, the expression of IL-32 was significantly inhibited in peripheral blood leukocytes of patients with lung cancer." (PMID 38983267, 2024). "Moreover, in the lung cancer patient tissue, the expression of IL-32 and TIMP-3 was dramatically decreased at a grade-dependent manner compared to normal lung tissue." (PMID 29467412, 2018). "Indeed, recent studies indicate that the expression of IL-32 is significantly altered in lung cancer cells compared to normal cells." (PMID 26395996, 2016). "On the other hand, in lung cancer cells MMP 2 and 9 were also found to be induced by IL-32 but via NF-kB." (PMID 35281008, 2022). "In this study, we revealed that ectopic expression of miR-19a or miR-19b-1 modulated the expression of IL-related genes (including IL1B, IL11RA, IL20RB, IL6 and IL32) and suppressed IL6 production in lung cancer and NPC cells." (PMID 32308549, 2020). "In conclusion, our results revealed that a potential isoform of IL-32, IL-32γ inhibits CSC self-renewal and stem cell niche, which is relevant to the growth of tumors and the recurrence of lung cancer through downregulation of the ITGAV-mediated STAT5 pathway." (PMID 31263095, 2019). "We further identified the effect of other isoforms of IL-32, including IL-32α and IL-32β, on TIMP-3 promoter methylation in A549 and NCIH460 lung cancer cell lines." (PMID 29467412, 2018). "In all lung cancer histotypes stromal leukocytes may also account for a considerable expression of IL-32, inside both, IL-32 positive and IL-32 negative tumors." (PMID 26395996, 2016).
myeloma (17 papers, 2012 to 2024). "Moreover, IL-32 expression correlated with expression of genes associated with a high proliferative index in myeloma." (PMID 35005550, 2022). "The microbiome stimulates protumorigenic IL32 expression in multiple myeloma (MM) cells via TLRs-NFkB, and Treg-derived IL32 promotes bladder cancer metastasis and immunosuppression together with TIGIT." (PMID 38343549, 2024). "IL-32 protein was similarly stabilized by MG132 treatment in three other myeloma cell lines: INA-6, IH-1, and OH-2." (PMID 37313466, 2023). "We previously showed that hypoxia promotes IL-32 expression through HIF1α in multiple myeloma cells." (PMID 37313466, 2023). "Depending on the triggering factors, the isoform, and cell type, IL-32 mediates its effect primarily intracellularly, but release of IL-32 by extracellular vesicles of myeloma cells has been described." (PMID 37727785, 2023). "As we found IL-32 to be upregulated by TLR activation in vitro, we next investigated if IL-32 is induced in primary myeloma cells in response to TLR agonists." (PMID 36875074, 2023). "IL-32 interacted with components of the mitochondrial respiratory chain and acted as an important regulator of myeloma cell metabolism." (PMID 35005550, 2022). "The significant reduction in proliferation upon IL-32 depletion in all three cell lines support that IL-32 has a proliferative effect on myeloma cells." (PMID 35005550, 2022). "Here we observe that IL-32-expressing myeloma cells have a gene signature indicative of highly proliferating cells with active OXPHOS and an immature phenotype." (PMID 35005550, 2022). "We found that endogenous intracellular IL-32 promoted survival and proliferation of myeloma cells in vitro and in vivo." (PMID 35005550, 2022). "Knocking out IL-32 in three myeloma cell lines reduced cell survival and proliferation in vitro and in vivo." (PMID 35005550, 2022). "IL-32 was expressed in a subgroup of myeloma patients with inferior survival, and primary myeloma cells expressing IL-32 had a gene signature associated with immaturity, proliferation, and oxidative phosphorylation." (PMID 35005550, 2022). "In consideration of high expression of IL-32 in multiple myeloma, we then measured the levels of VEGF and IL-32 in MM cells by ELISA." (PMID 34079757, 2021). "Both IL-32 mRNA and IL-32 protein were found to be increased in response to hypoxia in myeloma cells, and protein levels of IL-32 were shown to be dependent on the expression of hypoxia-inducible factor (HIF)-1α." (PMID 34199285, 2021). "MM-EVs from wild-type high IL-32-expressing JJN3 myeloma cells were found to promote osteoclast differentiation, whereas pro-osteoclasts treated with EVs from IL-32-knockout (KO) JJN3 cells did not." (PMID 34199285, 2021). "Deubiquitinase inhibitors promoted the degradation of IL-32 and may represent a strategy for reducing IL-32 levels in multiple myeloma." (PMID 37313466, 2023). "To further assess the relationship between IL-32 and TLRs in myeloma patients we compared TLR gene expression in MM primary cells with high- (n=80) or no/low expression of IL-32 (n=712) (IA13 CoMMpass dataset, cutoff: log2cpm>1.52, upper 10th percentile vs. lower 90th percentile)." (PMID 36875074, 2023). "Indeed, more recently, myeloma-derived IL-32 was shown to promote the formation of immunosuppressive, M2-like macrophages." (PMID 36875074, 2023). "The marker IL32 (logFC = 2.6) was a proliferation marker for malignant plasma cells in myeloma." (PMID 38328306, 2023). "Hence, loss of IL-32 in the MM cells cannot be compensated by microenvironmental-derived factors, and myeloma cells lacking IL-32 have reduced tumorigenic potential in vivo." (PMID 35005550, 2022). "Furthermore, some recent data indicated that IL-32 induced anti-inflammatory cytokines, such as IL-10 and the immunosuppressive molecules such as IDO in macrophages through STAT3 and nuclear factor κB pathway, and promoted multiple myeloma development." (PMID 34414188, 2021).
myeloma (continued). "Finally, patients with focal bone lesions assessed by magnetic resonance imaging were found to have significantly higher IL-32 expression in myeloma cells than patients without bone lesions, suggesting that IL-32 may play a role in MM bone diseases." (PMID 34199285, 2021).